TRIM34 (tripartite motif containing 34)
Description:
Functions as antiviral protein and contributes to the defense against retroviral infections. Acts as a capsid-specific restriction factor with the help of TRIM5 and prevents infection from non-host-adapted retroviruses. During influenza A virus infection, promotes programmed cell death by targeting ZBP1 for 'Lys-63'-linked polyubiquitination. In turn, promotes ZBP1 recruitment of RIPK3 to mediate virus-induced programmed necrosis. Negatively regulates the function of mitochondria by enhancing mitochondrial depolarization leading to cytochrome c release and mitochondria-dependent apoptosis. Also promotes the formation of multinucleated giant cells by means of cell fusion and phagocytosis in epithelial cells.
Synonyms: IFP1; RNF21
Tractability: PROTAC: ubiquitination databases record sites on it.
Gene: Protein-coding gene on chromosome 11 (5,619,764 to 5,644,398, forward strand). Ensembl gene ENSG00000258659.
Subcellular location: Cytoplasm; Mitochondrion
Subcellular location (Human Protein Atlas): Centrosome; Nucleoli
Pathways (Reactome):
Immune System: Interferon gamma signaling
Gene Ontology:
Molecular function: identical protein binding; ubiquitin protein ligase activity; zinc ion binding
Biological process: innate immune response; regulation of gene expression; protein ubiquitination
Cellular component: cytoplasm; mitochondrion; cytosol
Genetic constraint (gnomAD): Loss-of-function variants: 42 observed, 40.32 expected, observed/expected ratio (o/e) 1.04, 90% interval 0.81 to 1.35. The upper end of that interval is the gene's LOEUF score, 1.35, which puts it in group 5 of 6, group 1 being the genes least tolerant of losing a copy. Missense variants: 556 observed, 599.63 expected, observed/expected ratio (o/e) 0.93, 90% interval 0.86 to 1. Synonymous variants: 200 observed, 213.23 expected, observed/expected ratio (o/e) 0.94, 90% interval 0.83 to 1.05.
Homologues: Orthologues: chimpanzee TRIM6 (99% identical), mouse Trim34a (67% identical), mouse Trim34b (67% identical), guinea pig TRIM34 (67% identical), rat Trim34 (66% identical), pig TRIM34 (63% identical). Paralogues in human: TRIM22 (59% identical), TRIM6 (57% identical), TRIM5 (54% identical), TRIM68 (34% identical), TRIM21 (31% identical), TRIM38 (30% identical), TRIM60 (28% identical), TRIM58 (27% identical), TRIM39 (27% identical), TRIM27 (26% identical), TRIM11 (26% identical), TRIM75 (25% identical), and 68 more.
Diseases named in the same sentence as TRIM34 in open-access papers:
TRIM34 is named in the same sentence as 14 diseases in open-access papers, as found by Europe PMC text mining. Sharing a sentence is not in itself a finding about the gene and the disease. The quoted sentences say what the papers report.
HIV-1 infection (3 papers, 2020 to 2023). The type species of lentivirus and the etiologic agent of acquired immunodeficiency syndrome (AIDS). "RTEL1 is linked to pulmonary fibrosis, TRIM34 plays a role in restricting HIV-1 infection, PPP2R2A is a potential therapeutic target, and IRF7 shows high expression in certain COVID-19 patients, underlining the diverse implications of these genes in the context of SARS-CoV-2 infection." (PMID 38681774, 2023). "The tripartite motif-containing protein 34 (TRIM34), a paralog of the well-known TRIM5α, has also been shown to inhibit HIV-1 infection by targeting the CA protein." (PMID 33572761, 2021). "Recent studies have found that Daxx expression is upregulated during HIV-1 infection and suggest that Daxx interacts with CypA-bound capsid and recruits various restriction factors, such as TNPO3, TRIM5α, and TRIM34." (PMID 33572761, 2021). "Our results identify TRIM34 as an HIV-1 CA-targeting restriction factor and highlight the potential role for heteromultimeric TRIM interactions in contributing to restriction of HIV-1 infection in human cells." (PMID 32282853, 2020). "Indeed, consistent with a requirement of TRIM5α for the TRIM34-medicated restriction, we find that knockout of either TRIM34 or TRIM5α is sufficient to rescue infection with the N74D capsid mutant while neither knockout has a significant effect on WT HIV-1 infection." (PMID 32282853, 2020).
glioma (2 papers, 2022 to 2023). A benign or malignant brain and spinal cord tumor that arises from glial cells (astrocytes, oligodendrocytes, ependymal cells). "To date, the expression and role of TRIM34 in gliomas was poorly reported, using a similar approach; through differential analysis, we revealed that TRIM34’s expression in glioma samples and their different histopathological subtypes are significantly up-regulated." (PMID 37367937, 2023). "However, since other TRIM molecules mentioned in our study, except for TRIM34 and TRIM5, have already been validated in glioma in vitro experiments from previous studies, we focused our investigations on TRIM34 and TRIM5." (PMID 37367937, 2023). "Although having not been reported in glioma-related research, TRIM34, PCGF2, TLE3, and TRIM17 have been revealed to contribute to the carcinogenesis of other cancers." (PMID 35832194, 2022).
viral infection (2 papers, 2023 to 2026). "Thus, we propose that despite the lack of an overt, positively-selected site of viral interface on TRIM34, TRIM34 restricts viral infection through interaction with the rapidly-evolving TRIM5 protein." (PMID 37608289, 2023). "These TRIM34-mediated effects could be further exploited to develop new antiviral drugs against IAV, and potentially other viral infections." (PMID 42160298, 2026).
breast carcinoma (1 paper, 2012). "Whereas IFITM2 and TRIM34 have both been described to be induced by interferon but their role in carcinogenesis has not been studied, both LSP1 and PRKCDBP has been before associated with breast cancer." (PMID 23118876, 2012).
colitis (1 paper, 2021). Inflammation of the colon. "This phenotype makes mice more susceptible to DSS-induced colitis and inflammation-associated colorectal cancer, suggesting that TRIM34 in IECs plays an important role in maintaining the integrity of intestinal barrier, and in preventing severe colitis and tumorigenesis." (PMID 34956195, 2021).
cutaneous melanoma (1 paper, 2023). A primary melanoma arising from atypical melanocytes in the skin. "However, four genes, i.e., HPDL, GRIPAP1, GBP2, and TRIM34, have been reported to exhibit prognostic significance with respect to melanoma for the first time, while HAPLN3, CCL8, FCGR2A, and IFITM1 have been reported to relate with the initiation and immune microenvironment of cutaneous melanoma." (PMID 36818162, 2023).
infection (4 papers, 2020 to 2023). The state of being infected such as from the introduction of a foreign agent such as serum, vaccine, antigenic substance or organism. "Our results show that TRIM34 is an antiviral effector that blocks infection of an HIV with a particular mutation in capsid." (PMID 32282853, 2020). "To ask if TRIM34 blocks infection before reverse transcription, similar to rhesus TRIM5α, we infected control and TRIM34-overexpressing THP-1 cells and assayed viral DNA accumulation through a qPCR assay that detects HIV-1 reverse transcription products." (PMID 32282853, 2020). "We measured infection of these TRIM34-KO cells by the HIV-1 N74D and HIV-1 A77V CA mutants as compared to a WT HIV-1 control." (PMID 32282853, 2020). "Similar to our results in THP-1 and primary CD4+ T cells, infection with the HIV-1 N74D capsid mutant can be rescued by knockdown of either TRIM34 or TRIM5α in MoDCs." (PMID 32282853, 2020). "We infected the control and TRIM34-KO pools with both WT and N74D viruses and measured infection levels after 2 days by flow cytometry." (PMID 32282853, 2020). "Infection of these TRIM34-overexpressing, TRIM5-KO THP-1 pools demonstrates that the restriction of viral replication measured for the HIV-1 N74D capsid mutant is lost when TRIM5α is missing." (PMID 32282853, 2020). "Furthermore, we demonstrated that Daxx associates with incoming HIV-1 cores at 2 h post infection and resides within a complex containing CypA, TNPO3, TRIM5α, and its recently identified cofactor TRIM34." (PMID 32545337, 2020). "Therefore, as predicted for a restriction factor, overexpression of TRIM34 in THP-1 inhibits infection of cells by the HIV-1 N74D CA mutant virus." (PMID 32282853, 2020). "A further implication of the interaction of TRIM34 and TRIM5α is that TRIM34 may play a role in sensing infection, the pattern recognition function of TRIM5α." (PMID 32282853, 2020). "Infection with the N74D CA mutant can be rescued by TRIM34 knockout in CD4+ T cells." (PMID 32282853, 2020). "In contrast to infection with HIV-1 N74D CA, we find that infection of TRIM34-overexpressing cells is equivalent to WT cells for the HIV-1 A77V mutant." (PMID 32282853, 2020). "We identified TRIM34, a TRIM5 paralog, as an HIV-1 restriction factor capable of inhibiting infection by an HIV-1 N74D capsid mutant virus as well as several lentiviruses from monkeys." (PMID 32282853, 2020). "Notably, multiple antiviral proteins were also dramatically decreased in PAMs during the PRRSV-ADE infection, including ISG15, ISG20, IFIT1 (ISG56), IFIT2 (ISG54), IFIT3 (ISG60), IFIT5 (ISG58), OAS1, Mx1, RSAD2, TRIM22, TRIM25 and TRIM34, except for TRIM52." (PMID 36680075, 2022). "Importantly, while we initially identified TRIM34 in a screen for IFN-induced genes that block the N74D virus, these data suggest that TRIM34 is actually a constitutive block to infection whose activity is IFN-independent." (PMID 32282853, 2020). "Thus, we find that TRIM34 is a novel inhibitor of HIV-1 and SIV capsids that acts in conjunction with TRIM5α to limit infection of primary T cells." (PMID 32282853, 2020). "Since TRIM34 restriction depends on TRIM5α, we tested the hypothesis that TRIM34 and TRIM5α colocalize with each other and with incoming HIV-1 capsids during infection." (PMID 32282853, 2020). "Unlike TRIM5α inhibition of wild type HIV-1 capsids, TRIM34 is a constitutive inhibitor of the N74D CA mutant as KO rescues infection of the N74D virus even in the absence of IFN treatment 2.0-Fold (P<0.001)." (PMID 32282853, 2020). "We do not observe any rescue of WT infection on knockout of TRIM34 (ns)." (PMID 32282853, 2020).
tumor (3 papers, 2009 to 2023). "Several genes are contained within this interval that might be involved in brain development and/or tumor suppression, including TRIM3 and a cluster of genes encoding the more distantly related TRIM5, TRIM6, TRIM22, and TRIM34 genes." (PMID 19250537, 2009).
cancer (2 papers, 2022 to 2024). A tumor composed of atypical neoplastic, often pleomorphic cells that invade other tissues. "However, TRIM6 and TRIM34 individually encode ubiquitin ligases that may play roles in cancer and placenta development." (PMID 38912065, 2024).
TRIM34 also shares sentences with these, for which no sentence is quoted: COVID-19 (1 paper); melanoma (1); pulmonary fibrosis (1); tauopathy (1); Type 2 Diabetes (1).